IL2 (interleukin 2)
Diseases named in the same sentence as IL2 in open-access papers (continued):
Sharing a sentence is not in itself a finding about the gene and the disease.
COVID-19 (continued). "However, COVID-19-recovered older participants (n = 51) had greater antibody and T-cell responses, including IFNγ+ and IFNγ+IL-2+TNFα+-specific CD4+ T cells (p < 0.0001), as well as TNFα+-specific CD8+ T cells (p < 0.001), than COVID-19-naive older adults." (PMID 34868051, 2021). "Antigen-specific CD4+ T cells expressing memory markers as well as IL-2, IFN-γ, TNF-α, and CD154 were markedly increased in COVID-19–recovered individuals compared with healthy donors, but the relative frequency of these cells decreased at the 6.1-mo time point (clusters 2, 3, 4, and 6)." (PMID 33533915, 2021). "Recently, it was observed in a study that in normal patients, there was a lower level of classical inflammatory cytokines like G-CSF, CCL-20, IL-1β, IL-2, IL-6, IL-15, TNF-α, and TGF-β while at the same time, there was a higher plasma level of GM-CSF and CXCL-10 in COVID-19 patients." (PMID 34305892, 2021). "To investigate the role of cytokines and chemokines in the inflammatory status of COVID-19 and MIS-C, we measured plasma levels of IL-1ß, IL-2, IL-4, IL-5, IL-6, IL-10, TNF-α, IL-17A, IFN-α, IFN-γ, CXCL10/IP-10, CXCL8/IL-8, CXCL9/MIG, CCL5/RANTES, and CCL2/MCP1." (PMID 33841438, 2021). "Most COVID-19 patients exhibit increased circulating levels of IL-6, IL-1b, and TNF, as well as IL-2, IL-8, reflecting the disease severity, which results in massive systemic immunosuppression and in lymphopenia and neutrophilia, two key hematological features of COVID-19." (PMID 33815868, 2021). "Higher blood levels of inflammatory biomarkers (e.g. CRP) and cytokines (e.g. IL2, IL7, IL10, etc.)have been reported in COVID-19 patients admitted to the ICU3, and IL6 and IL10 have been determined to be strong discriminators for severe disease and death, consistent with our findings." (PMID 33627696, 2021). "Monocytes were negatively correlated with IL-2, IL-4, and TNF-α in the COVID-19 severe group." (PMID 34712741, 2021). "Studies have shown that compared with that of mild cases, plasma levels of IL2, IL6, IL7, IL10, G-SCF, IP10, MCP1, ferritin, and TNFα in severe cases of COVID-19 were elevated, indicating that the participation of these cytokines contributes to the pathogenesis of deterioration." (PMID 34305916, 2021). "We have found fifteen cytokines that remain upregulated in convalescent COVID-19 individuals one month after infection (IL-1α, IL-3, IL-10, IL-12p70, CCL7, IFN-α2, bFGF, LIF, TRAIL, IL-2, IL-4, IL-5, IL-12p40, IL-17 and MIF) indicating a strong activation of the immune response." (PMID 34681885, 2021). "We observed several folds of increases in the SARS-CoV-2 antigen-reactive T cells over the control T cells, indicating that DCs presenting the SMENP epitopes (CTL + COVID-19) elicited a strong anti-SARS-CoV-2 T-cell response in both CD4 and CD8 T cells (CD107a, IFN-γ, TNF-α, and IL-2)." (PMID 34451952, 2021). "However, in COVID-19 multifunctional activated T cells secreting two of the three cytokines IFN-γ, IL-2, and TNF-α were reduced whilst T cells producing all three were non-functional." (PMID 33936053, 2021). "In line with this, in an in vitro pilot study we showed that 5-FU may lower the burden of MDSC in severe COVID-19 patients, casing a lowered production of IL-10, IL-8, IL-17, and Th2 cytokines, while increasing the production of IFN-γ and IL-2." (PMID 33692788, 2021). "Additionally, there were higher correlations between IL-2 and IL-4, TNF-α and IL-2, TNF-α and IL-4, TNF-α and IFN-γ, and CD16+CD56+NK cells and various subsets of T cells in COVID-19 patients." (PMID 34712741, 2021). "Usually, patients who have COVID-19 have a decreased number of helper T cells, cytotoxic T cells, regulatory T cells, and natural killer (NK) cells, but increased leptin, TNF-α, interleukin-1 (IL-1), interleukin-2 (IL-2), and interferon-gamma (IFN-γ)." (PMID 34064950, 2021).
COVID-19 (continued). "TNF-α, IFN-γ, and IL-2 were also higher while IL-4 was lower in severe COVID-19 cases than in mild cases, but the difference was not significant." (PMID 32669467, 2020). "Clinical studies show that the levels of IL-2, TNF-α, IFN-γ, IP-10, MCP-1and other pro-inflammatory cytokines are significantly increased in severe or critical patients with COVID-19, while SARS-CoV-2 infection also increases secretion of anti-inflammatory cytokines (IL4 and IL10)." (PMID 32665783, 2020). "Furthermore, there is a lower percentage of CD107a + NK, IFN-γ+ NK, IL-2+ NK, and TNF-α+ NK cells in COVID-19 patients." (PMID 32983152, 2020). "Interestingly, the production of cytokines by CD4+ (mainly IL-2 and IFN-γ and trace amounts of IL-4, IL-5, IL-13, or IL-17α) was also reported in COVID-19 convalescents." (PMID 32916812, 2020). "Principle behind use: severe cases of COVID-19 are characterized by a cytokine storm defined as a sudden production of cytokines, such as IL-2, IL-7, IL-10, granulocyte colony-stimulating factor (G-CSF), MCP1, MIP-1a, and TNF-α, secondary to the upregulation of the inflammatory process in COVID-19." (PMID 32953365, 2020). "Studies have established that increased levels of IL-1β, IL-2, IL-6, IL-10, IFN-γ, TNF, IFN-γ-inducible protein 10 (IP-10), granulocyte macrophage-colony stimulating factor (GM-CSF), and monocyte chemoattractant protein-1 (MCP-1) correlate with COVID-19 severity." (PMID 39940907, 2025). "Moreover, IL-2 levels were significantly lower in COVID-19 non-survivors compared to survivors, indicating a worse prognosis for the disease." (PMID 41194029, 2025). "The results showed that IL-1β, IL-2, IFN-β, IFN-γ, IL-17, GM-CSF, and TFN-α had a slightly higher correlation with metabolic phenotype 2 in non-survivors, indicating a potential association with COVID-19 mortality outcome." (PMID 41002992, 2025). "The study identified IL-6, TNF, IL-1β, IL-10, and IL-2 as the five most distinctive cytokines that could effectively differentiate between individuals who had COVID-19 (including those with long COVID) and those who had never been exposed to the virus." (PMID 39518964, 2024). "The pro-inflammatory cytokines that signal via the JAK-STAT signalling pathway include IL-2, IL-6, IL-8 and TNF-α, all of which are elevated in severe COVID-19, as well as antiviral or anti-inflammatory cytokines such as IFN-γ and IL10, which are also elevated in severe COVID-19." (PMID 39051370, 2024). "Except for IL-8 decreased in the second trimester after infected with SARS-CoV-2, IL-2, TNF-α, TNF-β, IFN-γ, IL-4, IL-5, IL-6, IL-10, IL-17A, IL-17F, IL-22, IL-1β and IL-12p70 didn't change in the three trimesters between healthy pregnancies and pregnant women with COVID-19." (PMID 39113896, 2024). "Although one long COVID-19 patient had a negative IL-2 T cell response despite fulfilling clinical criteria, this could be explained by the limited sensitivity of the assay." (PMID 39073768, 2024). "Overall, our study shows that the development of CRS requires the involvement of multiple immune cells, and IL-2, TNF-α, and IFN-γ may act as the primary factors in triggering CRS, providing promising avenues for clinical interventions for patients with COVID-19." (PMID 39359733, 2024). "Therefore, the interplay between IL-2 and TNF-α/IFN-γ might be crucial in mediating the synergistic effect of IL-2 and spike protein in inducing CRS in patients with COVID-19." (PMID 39359733, 2024). "We aimed to evaluate the efficacy and safety of ixekizumab (IL-17 inhibitor), low-dose IL-2, and colchicine (indirect IL-6 inhibitor) combined with SOC treatment in comparison with SOC alone for the treatment of hospitalized patients with moderate-to-critical COVID-19." (PMID 37075454, 2023).
COVID-19 (continued). "Furthermore, recently it was discovered that natural killer (NK) cells and CD8+ T cells of patients with COVID-19 have a higher expression of the NK cell inhibitory receptor, NKG2A, which is characterized by lower intracellular amounts of CD107, IFN-γ, IL-2, TNF-α, and granzyme B." (PMID 36679947, 2023). "However, the results of that study showed that IL-2 and IL-4 are not significantly altered in severe and nonsevere COVID-19 patients." (PMID 37649897, 2023). "The role of ∝2-M in COVID-19 has been proposed based on its versatility; specifically, in its tetrameric form, it is able to inhibit all four classes of proteases, while in its dimeric form, it shows increased interaction with mediators of inflammation, such as TNF-∝, Il-2, and IL-6." (PMID 37371071, 2023). "Our results indicate that both naïve and COVID-19-recovered HD patients maintain strong cellular and humoral immune responses after receiving a third dose (booster), which is comparable or higher (significant increased at V3+3M for IFN-γ and IL-2) to HV individuals." (PMID 37111331, 2023). "This study demonstrated that IL-2 did not correlate with COVID-19 severity and pulmonary fibrosis." (PMID 37649897, 2023). "An elevated concentration of soluble IL-2R may be able to scavenge IL-2, indicating that low-dose IL-2 therapy was not the best course of action for treating COVID-19." (PMID 36992283, 2023). "In this regard, it has been reported that post-COVID-19 patients develop a cytokine syndrome characterized by an imbalance of pro-inflammatory and anti-inflammatory cytokines, such as IL-17 and IL-2, and IL-10 and IL-4, compared with COVID-19 patients without sequelae." (PMID 36836568, 2023). "As the IL2-AIS was initially identified in the DILfrequency study using a targeted panel of 565 transcripts designed for profiling T and NK cells, we sought to understand the observed changes in the broader transcriptional landscape of immune cells in COVID-19 patients." (PMID 37700317, 2023). "Furthermore, the levels of MIP-1α, IL-6, and IL-2 were not altered throughout the observation period in the COVID-19 group between different time points." (PMID 37034572, 2023). "Conversely, subjects with decreased IL-2 and IFN-gamma expression and increased PD-1 production in CD4+ and CD8+ T cells in response to polyclonal stimuli tended to display the most severe form of COVID-19, including respiratory distress and mechanical ventilatory support needing." (PMID 35860236, 2022). "However, IL-2 secretion was only significantly higher in adults with moderate COVID-19 (51.8 versus 3.7 pg/ml; P=0.0026) and not in adults with mild symptoms compared to infected children." (PMID 35197982, 2022). "Our results showed that serum IL-2, IL-4, IL-6, and IL-10 levels were elevated in COVID-19 patients compared to healthy controls, and IL-6, IL-8, and IL-10 levels were increased in severe COVID-19 cases compared to nonsevere patients." (PMID 35540724, 2022). "Current clinical studies have shown that the expression levels of inflammatory factors (IL-2, IL-7, IFN-γ, and TNF-α) positively correlate with the severity of COVID-19, suggesting that PLA2G4A may be a key target in the development of COVID-19." (PMID 36210820, 2022). "Interestingly, obviously elevated IL-2, IL-8, IL-10, TNF-α, and IL-12p70 were observed in symptomatic patients with COVID-19 compared with asymptomatic carriers, which were consistent with the results in that of patients with COVID-19." (PMID 35685940, 2022). "In response to polyclonal stimuli, basal production of interleukin-2 (IL-2) and interferon (IFN-) gamma significantly decreased, and the programmed cell death protein 1 (PD-1) increased in CD4+ and CD8+ T cells from participants who posteriorly developed severe COVID-19 compared to mild cases." (PMID 35860236, 2022).
COVID-19 (continued). "To obtain a complete picture of the adaptive immune response to anti–COVID-19 vaccination, we evaluated the antigen-specific CD4+ T cell response to SARS-CoV-2 spike protein peptides, monitoring CD154 expression and the production of IL-2, IFN-γ, and TNF-α upon in vitro stimulation." (PMID 35139036, 2022). "The increased levels of soluble IL-2R could potentially scavenge IL-2, suggesting low-dose IL-2 therapy was not the optimal regimens for COVID-19 treatment." (PMID 35874688, 2022). "Indeed, higher levels of IFN-α, IFN-β, IL-2, and IL-12 are distinctive features of asymptomatic and mild as opposed to severe COVID-19 (Masood and others 2021; Tjan and others 2021)." (PMID 35674675, 2022). "In fact, in critically ill COVID-19 patients, IFN-I and INF-III levels and IFN-stimulated gene responses are lower compared with other respiratory viruses, while proinflammatory cytokines, including interleukin-2 (IL-2), IL-6, and tumor necrosis factor (TNF), are increased." (PMID 34769508, 2021). "The results showed that there were significant differences in the levels of IL-2, IL-10, absolute count of lymphocyte subsets (CD3+ T cells, CD3+CD4+ T cells, CD3+CD8+ T cells, and CD19+ B cells), CD16+CD56+ NK cells, and neutrophils between patents with COVID-19 and cancers." (PMID 34712741, 2021). "In addition, there were higher correlations between IL-2 and IL-4, TNF-α and IL-2, TNF-α and IL-4, TNF-α and IFN-γ, and NK cells and T cells in COVID-19 patients, and there was a higher correlation between CD3+CD4+ T cells and CD19 + T cells in cancer patients." (PMID 34712741, 2021). "PIMS-TS children had significantly elevated levels of cytokines, IFNγ, IL-2, TNFα, IL-1α, IFNα, IFNβ, IL-6, IL-15, IL-17A, GM-CSF, IL-10, IL-33 and IL-Ra; elevated chemokines, CCL2, CCL19, CCL20 and CXCL10 and elevated VEGF, Granzyme B and PDL-1 in comparison to COVID-19, seropositive and controls." (PMID 33813138, 2021). "A significant increasing trend of IL-1β, IL-1ra, IL-2, IL-4, IL-5, IL-6, IL-7, IL-8, IL-10, IL-12(p70), IL-15, IL-17, FGF-b, G-CSF, GM-CSF, IFN-γ, IP-10, MCP-1, MIP-1α, PDGF, TNF-α, and VEGF was observed in the three groups (Controls ≤ Mild COVID-19 ≤ Severe COVID-19)." (PMID 34675240, 2021). "In patients with COVID-19 hospitalized in intensive care units, elevated serum levels of IL-1β, IL-7, IL10, IL-17, IL-2, IL-9, Th17, IFN-γ, GM-CSF, G-CSF, IL-8, TNF-α, MIP1B, MCP1, MIP1A, and IP10 were observed, suggesting that the relation between periodontitis and COVID-19 may be established." (PMID 34068221, 2021). "The correlation coefficients for TNF-α and IL-2, and TNF-α and IFN-γ were higher in the COVID-19 group than that in the cancer group, while the correlation coefficients between CD3+CD4+ T cells and CD19+ B cells were higher in the cancer group than that in the COVID-19 group." (PMID 34712741, 2021). "Moreover, the serum levels of IFN-γ, TNF-α, IL-2, IL-4 and IL-10 were not correlated with disease severity among COVID-19 patients." (PMID 34123873, 2021). "The higher prevalence of IL-2-producing SARS-CoV-2-specific cell clones could support the predominance of CD4+, rather than CD8+, T lymphocytes as expression of immune memory in patients who overcome COVID-19." (PMID 34962970, 2021). "However, to the best of the authors’ knowledge, there is still no widely available IL-2 agonist on the market for SLE or COVID-19 therapy." (PMID 33193418, 2020). "Several studies have shown the responses of T cells from COVID-19 patients to different SARS-CoV-2-derived peptides matching sequences of S and N proteins; these cellular responses included increased expression of several cytokines such as IFN-γ, IL-2, and IL-17 in CD4+ cells." (PMID 33198287, 2020).
COVID-19 (continued). "In this regard, the release of anti-inflammatory cytokines from skeletal muscle contraction, cortisol elevations, prostaglandin E2, and soluble receptors against TNF and IL-2, and increased mobilization of immunoregulatory leukocyte subtypes may be relevant in attenuating the CRS in COVID-19." (PMID 33212762, 2020). "Another study showed a similar trend, with plasma concentrations of IL-2, IL-7, IL-17, IL-10, MCP-1, MIP-1A, IP10, and TNF-α being observed to be higher in COVID-19 patients undergoing treatment in intensive care units than in any other category of COVID-19 patients." (PMID 32984253, 2020). "Notably, IL-2 plays a key role in the proliferation of T cells and in the generation of effector and memory T cells, suggesting that the transcript switch of IL2 may affect the activation of T cells in severe COVID-19 patients." (PMID 35421082, 2022). "However, PD-1 expression conditioned IL-2 and IFN-gamma production in cytotoxic T cells, which expressed higher IL-2 and IFN-gamma levels in PD-1 negative cells than CD3+CD8+PD-1+ T cells independently of having been analyzed in participants that posteriorly developed either mild or severe COVID-19." (PMID 35860236, 2022). "In contrast, COVID-19 negative individuals showed lower-magnitude responses for TNF, IL-10, and IL-17A but exhibited multiple peaks in IL-2, IL-6, and IFN-γ production." (PMID 40406109, 2025). "Overall, we found an increase in anti-SARS-CoV-2 serum antibody levels over time and no decrease in IL-2- or IFN-γ-producing cells, which suggests maintenance of a robust functional immune system post-COVID-19 in patients with and without long COVID." (PMID 41324571, 2025). "A strong relationship was observed between certain inflammatory markers, including IL-1β, IL-2, IFN-β, IFN-γ, IL-17, and GM-CSF, as well as several metabolites, particularly in COVID-19 non-survivors, such as LysoPCs, 3-hydroxykynurenine, and serotonin." (PMID 41002992, 2025). "PLWH with COVID-19 with an undetectable VL had higher concentrations of IL-2, IL-4, and IFN-γ than PLWH without COVID-19 with a detectable VL." (PMID 39597537, 2024). "Higher concentrations of IL-2, IL-6, IL-8, and TNF-α were also reported in ICU patients with COVID-19 in comparison to non-ICU patients." (PMID 38707035, 2024). "Previous studies have explored the correlation between serum levels of pro-inflammatory (IL-2, IFN-γ, TNF-α) or anti-inflammatory cytokines (IL-4 and IL-10) with clinical or negative outcomes in individuals with COVID-19." (PMID 38601541, 2024). "More than 98% of the HCWs with severe COVID-19 had cytokine levels (IFN-γ, IL-10, IL-2 and IL-4) in the normal ranges." (PMID 36908474, 2023). "In addition, we showed that the cytokines IFN-γ, IL-2, IP-10, IL-1β, IL-6, IL-8, and TNF could discriminate the status of SARS-CoV-2 infection or exposition, and also it highlighted the high levels of pro-inflammatory IL-1β and IL-6 in long-COVID-19 when compared to the unexposed group." (PMID 37018291, 2023). "Remarkably, COVID-19 patients requiring intensive care unit (ICU) admission presented higher levels of CCL2, CXCL10, IL-2, IL-7, IL-10 and TNF-α than non-ICU patients, hinting the linkage between the cytokine storm and COVID-19 deterioration." (PMID 37251383, 2023). "In the acute COVID-19 group, younger patients had higher levels of TNF-α, and patients without comorbidities had higher levels of TNF-α, IL-4 and IL-2 (p<0.05)." (PMID 35846757, 2022). "We found that children with convalescent COVID-19 produced cytokines typical of a Th1 response (IFN-γ and IL-2) following stimulation with both spike and non-spike antigens." (PMID 35044955, 2022). "In the study, the results showed that the levels of pro-inflammatory cytokines (IL-2, IL-4, IL-6, TNF-α, and IFN-γ) were not different between mild, moderate, and severe/critical groups of children with COVID-19." (PMID 36294306, 2022).